G6PD (glucose-6-phosphate dehydrogenase)
Diseases named in the same sentence as G6PD in open-access papers (continued):
Sharing a sentence is not in itself a finding about the gene and the disease.
tumor (continued). "Inhibiting G6PD could suppress tumor cell proliferation, promote cell death, reverse chemoresistance, and inhibit metastasis, suggesting the potential of G6PD as a target for anti-tumor therapeutic strategies." (PMID 38139067, 2023). "Then, we verified if RMRP can exert its tumor-promoting function through the miR-206/G6PD axis." (PMID 37958478, 2023). "Glucose-6-phosphate dehydrogenase (G6PD) is verified to be an independent risk factor related to the adverse outcomes of HCC, and exacerbates tumor growth, invasion, and metastasis, along with reduced ferroptosis through suppressing cytochrome P450 oxidoreductase (POR)." (PMID 37124203, 2023). "In addition, recent studies suggest that G6PD inhibitors have a significant effect on the reduction of tumor progression and chemotherapy resistance." (PMID 38139067, 2023). "Additionally, analysis of drug sensitivity showed that high expression of G6PD was involved in anti-tumor drug resistance." (PMID 37601657, 2023). "It is noteworthy that while G6PD is an attractive target for anti-tumor therapy, merely blocking G6PD might be insufficient." (PMID 38139067, 2023). "Exposure to Fak-depleted CAF cellular medium enhances glycolysis in tumor cells by upregulating glycolysis enzymes including pyruvate kinase, as well as glucose-6-phosphate dehydrogenase (G6PD) and 6-phosphogluconate dehydrogenase (6PGD) in the oxidative branch of pentose-phosphate pathway (PPP)." (PMID 35159011, 2022). "In addition, we review signaling pathways that regulate G6PD and evaluate the role of oncogenic signals that lead to the reprogramming of PPP in tumor and non-neoplastic diseases as well as summarize the inhibitors that target G6PD." (PMID 36091812, 2022). "To explore the effects of Trx-1 and G6PD inhibition on tumor growth, we used dehydroepiandrosterone (DHEA, an inhibitor of G6PD) 29, 1-methylpropyl 2-imidazolyl disulfide (PX-12, an inhibitor of Trx-1) 30 and combination with 2DG to treat CRC xenografts in nude mice." (PMID 36147458, 2022). "This illustrates that PTEN controls G6PD expression through two steps by inhibiting G6PD pre-mRNA splicing, which suggests that G6PD is a key regulatory factor of PTEN in controlling tumor progression and implies that G6PD is a valuable target for anticancer treatments." (PMID 35207558, 2022). "Interestingly, although T cells also proliferate rapidly upon activation, blockade of G6PD appears to generate superior CD8+ effector T cells which mediated a stronger tumor antigen-specific response, as well as increased proinflammatory cytokine secretion." (PMID 36479131, 2022). "Genetic blockade of G6PD in vivo results in reduction of tumor growth within bone." (PMID 35213227, 2022). "G6PD, an important rate-limiting enzyme of the pentose phosphate, was essential for tumor growth." (PMID 35924040, 2022). "Moreover, we found that the combined inhibition of Trx-1, G6PD, and glycolysis produced a substantial anti-tumor effect in CRC xenografts in vivo." (PMID 36147458, 2022). "As a consequence, cells with a high demand for NADPH, such as tumor cells, exhibit a metabolic vulnerability that could be targeted by the inhibition of G6PD as a therapeutic strategy." (PMID 36091812, 2022). "However, it was recently observed that G6PD can regulate cell transformation, proliferation, apoptosis, and angiogenesis in tumour tissues." (PMID 35712981, 2022). "Additionally, G6PD, HELLS, RRM2, and STMN1 were positively associated with higher tumor stage, grade, age, sex, and ethnicity, suggesting an influential contribution to the pathogenesis of HCC." (PMID 36304446, 2022). "Whereas, high expression of G6PD promotes tumor growth by generating ribo-5-phosphate and NAPDH." (PMID 36712870, 2022). "Because of its key metabolic role, G6PD is also involved in tumor pathogenesis where it has been reported to modulate proliferation, metastasis, chemoresistance, immune activation, and tumor ferroptosis." (PMID 36248857, 2022).
tumor (continued). "In conclusion, G6PD might be involved in the immune invasion of the tumour microenvironment and in the attenuated anti-tumour response in HCC treatment." (PMID 35712981, 2022). "Activation of G6PD, a ‘metabolic checkpoint’ that controls glucose metabolic flux partitioning between aerobic glycolysis and the pentose phosphate pathway, increases Gzmb expression in tumor-specific CTLs." (PMID 36569893, 2022). "The tumor weight in sh-G6PD group was notably restrained compared to sh-NC group." (PMID 33514309, 2021). "CCL5 and CCL18 up-regulate the activity of various glycolysis factors, including lactate dehydrogenase A (LDHA) and glucose-6-phosphate dehydrogenase (G6PD), which can advance glycolysis in tumor cells, lead to accumulation of lactic acid in TME and restrain the immune system’s anti-tumor reaction." (PMID 34368156, 2021). "To address whether TSP50‐mediated G6PD activity changes are important for tumour growth, we performed xenograft experiments using L02 cell." (PMID 33630390, 2021). "Additionally, the tumour size and tumour weight are decreased in the mice injected with cell expressing G6PD K171Q." (PMID 33630390, 2021). "Indeed, we observed a reduction of both NRF2 and G6PD expression also in non-tumor cell lines such as MDCK, HEK293 and BEAS-2B indicating the modulation of NRF2 pathway also in normal infected cells." (PMID 35071051, 2021). "Further enzymatic activity assay confirmed the inhibition of G6PD by polydatin in tumor tissues." (PMID 34354953, 2021). "The relative expression of TSP50 and G6PD is consistent with that in tumour cells." (PMID 33630390, 2021). "Furthermore, the expression level of HPV16 E6 was positively correlated with the expression levels of G6PD in host tumor tissues (correlation analysis, r = 0.89, p < 0.05)." (PMID 34692493, 2021). "G6PD overactivation in tumor cells is regulated at the transcriptional or posttranslational level." (PMID 34354953, 2021). "Moreover, G6PD inhibitor exhibited tumor-suppressor activities in ccRCC and attenuated the growth of ccRCC cells both in vitro and in vivo." (PMID 33041664, 2020). "Here, the sustained activation of NRF2 due to KEAP1 LOF mutation was seen to promote tumor growth and upregulate the expression of PPP genes, including G6PD, TKT and PGD, through the epigenetic inhibition of miR-1 and miR-206, two repressors of metabolic gene induction." (PMID 32443774, 2020). "Moreover, G6PD along with both pSTAT3 and p65 were displayed high expression levels in tumor tissues compared with adjacent normal tissues." (PMID 33041664, 2020). "Serum G6PD activity may, therefore, be a useful tumor marker reflecting tumor progression and evaluating the response to treatment." (PMID 33361404, 2020). "Staining of more than 50% of tumor cells was defined as ‘G6PD high’." (PMID 33361404, 2020). "Serum G6PD activity significantly increased as the tumor stage progressed in samples obtained from pretreated patients (n=19, p=0.0064, Kruskal-Wallis test) and decreased after treatment including surgery, radiation or both (n=8 paired, p=0.030, paired-t test)." (PMID 33361404, 2020). "Moreover, immunohistochemistry staining was performed to analyze the expression of G6PD, pSTAT3, and p65 in tumor tissues and adjacent normal tissues." (PMID 33041664, 2020). "The present study shows that the combination of tumor and chemotherapy (C26 OXFU) leads to increased protein carbonylation that was associated with enhanced G6PD activity, likely due to an adaptive, though unsuccessful, response of the muscle to face the redox imbalance." (PMID 30823492, 2019).
tumor (continued). "Several studies showed that the inhibition of G6PD may result in the development of therapeutic strategies against tumour growth and metastasis." (PMID 30987650, 2019). "BAG3 protein directly binds to G6PD to exert the tumor suppressor-like function in HCCs." (PMID 31500396, 2019). "Finally, in silico studies showed a significant correlation between G6PD expression and tumour relapse/resistance in patients." (PMID 30987650, 2019). "G6PD enhances tumor growth by maintaining intracellular redox homeostasis." (PMID 31500396, 2019). "However, only G6PD was significantly over-expressed in tumor compared to normal tissues (P = 0.001)." (PMID 30603059, 2018). "Thus, both PFKL and G6PD contribute the proliferative effect of TAp73, and their simultaneous activation by TAp73 likely affords tumor cells a strong advantage during anchorage-independent growth." (PMID 30409970, 2018). "Furthermore, patient samples organized by tumor grade displayed a progressive increase in G6PD mRNA levels as determined using ANOVA (ANOVA, P-value = 6.79 × 10−7), indicating a strong association with tumor progression." (PMID 29904144, 2018). "Of note, in control cells, knocking down G6PD led to strong reduction in tumor growth." (PMID 30409970, 2018). "Also, G6PD protein level was notably increased in eight representative tumor compared with adjacent normal tissues." (PMID 28692052, 2017). "Also, the tail vein injection of PPMS polyplexes silenced G6PD expression and yielded effective inhibition of tumor growth compared to the scramble and PBS control groups in vivo." (PMID 28692052, 2017). "Higher expression of both G6PD and CD133 in tumor were associated with poor survival." (PMID 28596515, 2017). "Glucose-6-phosphate dehydrogenase (G6PD) overexpression in different tumor types." (PMID 28553614, 2017). "Knowing that ID1/G6PD signaling promoted tumor cell proliferation and chemoresistance in HCC, we wondered whether ID1/G6PD signaling could predict unfavourable prognosis in HCC patients." (PMID 29169374, 2017). "To address whether G6PD-mediated PPP pathway is important for Plk1-regulated tumor growth, we performed xenograft experiments using Hep3B and HeLa cells." (PMID 29138396, 2017). "Aberrant G6PD could stimulate cell proliferation and tumor growth by activating the G6PD-ROS-p-STAT3-CyclinD1 signaling pathway." (PMID 29312589, 2017). "Furthermore, it has been shown that inhibition of G6PD activity triggers the sensitivity of tumor cells against oxidative stress and consequently leads to an increased susceptibility of these cells to apoptosis." (PMID 27872579, 2016). "First evidence that reduction of G6PD activity may be capable to reduce tumor growth was given as early as in the 1970-ies; the same was recently approved by more modern methods." (PMID 27872579, 2016). "In addition, co-transfection of G6PD siRNA and miR-1 sponge partially reversed miR-1 sponge-induced reductions in cell viability and neoplasm growth." (PMID 27861141, 2016). "It has been shown that reduction of the G6PD activity in tumor cells up to 80% is sufficient for significant reduction of cell proliferation, migration and invasiveness as well as for significant decrease of colony forming efficiency; coincidentally the rate of tumor cell apoptosis increased." (PMID 27872579, 2016). "To determine whether G6PD glycosylation is important for tumor formation in vivo, we injected WT G6PD or S84V G6PD replacement A549 cells into immunocompromised mice and assayed their ability to form tumours." (PMID 26399441, 2015). "Additionally, aspirin (0.25–2.5 mM) acetylates and decreases the activity of glucose-6-phosphate dehydrogenase (G6PD), an enzyme involved in ribonucleotide biosynthesis and the positive control of tumor cell proliferation." (PMID 24005861, 2013). "The control patterns found support the hypotheses that the glucose-6-phosphate dehydrogenase and the Warburg effect are promising targets for tumor treatment." (PMID 20426867, 2010).
tumor (continued). "SBSN, ZNF-711 and G6PD have not previously been associated with tumor specific expression or carcinogenesis." (PMID 19997593, 2009). "Furthermore, the progressive suppression of ASCC2, ALKBH3, E2F1, and G6PD led to a marked decrease in their immunohistochemical staining scores, indicating reduced protein expression and altered cellular localization within the tumor microenvironment." (PMID 41484982, 2026). "Notably, G6PD expression was significantly elevated in tumor samples compared to normal tissues." (PMID 40307857, 2025). "Interestingly, knocking down G6PD inhibited HB tumor growth both in vitro and in vivo." (PMID 40303290, 2025). "Studies have shown that G6PD mutations in patients with AML may lead to redox imbalance, which, in turn, affects tumor cell growth and drug resistance, especially in FLT3 inhibitor therapy, where G6PD-driven redox metabolism promotes the development of drug resistance." (PMID 40299448, 2025). "This suggests that G6PD may modulate both immune activation and suppression within the tumor." (PMID 40116585, 2025). "Moreover, our previous research demonstrated that PBX3 could elevate G6PD expression, which in turn facilitates tumor cell glucose metabolic reprogramming through activating the pentose phosphate pathway." (PMID 40508020, 2025). "Additionally, G6PD expression is strongly linked to OS and the immune microenvironment in HCC, and its overexpression lowers ferroptosis in HCC, underscoring its potential as a tumor prognostic and therapeutic biomarker." (PMID 40465746, 2025). "Additionally, ITGB1 knockdown abrogated the expression of G6PD in tumor cells." (PMID 40685383, 2025). "By disrupting these events and inhibiting G6PD, tumor growth may be effectively limited." (PMID 39796677, 2024). "Furthermore, G6PD levels are elevated in many tumor entities, such as colorectal cancer." (PMID 38879607, 2024). "To further investigate whether Fra-1 induces chemoresistance in GC cells in vivo by modulating the PPP metabolic pathway, we performed immunohistochemistry on paraffin-embedded sections of transplanted tumor tissues from nude mice to assess Fra-1 and G6PD expression." (PMID 39624082, 2024). "Furthermore, the mRNA half-life of G6PD was reduced in tumor cells with METTL14 downregulation." (PMID 39138186, 2024). "Taken together, these results revealed that G6PD might be involved in tumor immune response." (PMID 37601657, 2023). "Therefore, G6PD may play a vital role in immune infiltration and may be a potential therapeutic target for tumor immunotherapy." (PMID 37601657, 2023). "Therefore, G6PD-mediated activation of the PPP may promote tumor metastasis through its ability to maintain redox homeostasis." (PMID 38139067, 2023). "Given these facts, targeting G6PD could potentially weaken tumor progression." (PMID 38139067, 2023). "G6PD is overexpressed in CRC patient specimens and predicts poor prognosis, and therefore, suppression of G6PD activity may be an important mechanism underlying the anti-tumour effects of aspirin." (PMID 37720350, 2023). "Therefore, G6PD is a possible target gene for RMRP to promote BLCA tumor formation." (PMID 37958478, 2023). "Considering G6PD as a therapeutic target could be a potential way to reduce tumor progression." (PMID 38139067, 2023). "In addition to tumor metabolism, G6PD can widely affect tumor cell proliferation and apoptosis." (PMID 37601657, 2023).
tumor (continued). "Therefore, it is reasonable to believe that the G6PD protein may have other biological functions in regulating tumor cell growth besides the enzyme activity of the PPP pathway." (PMID 37601657, 2023). "However, challenges remain in G6PD-based anti-tumor therapy." (PMID 38139067, 2023). "G6PD could enhance tumour growth by maintaining intracellular redox homeostasis." (PMID 34423480, 2021). "Moreover, G6PD inhibition exhibited tumor-suppressing activities in ccRCC, indicating that G6PD might be a potential therapeutic target for ccRCC treatment." (PMID 33041664, 2020). "Therefore, it was necessary to investigate whether G6PD activity inhibitors had an anti-tumor effect both in vitro and in vivo." (PMID 33041664, 2020). "Thus, G6PD is highly expressed in tumor cells compared to normal ones." (PMID 32842595, 2020). "However, when G6PD was knocked down, Plk1-enhanced tumor growth of Hep3B xenografts was markedly retarded, suggesting that G6PD was critical for Plk1-regulated tumor growth in mouse model." (PMID 29138396, 2017). "Furthermore, the combination of oxaliplatin treatment and G6PD knockdown by PPMS polyplexes resulted in the more potent anti-tumor activity compared with oxaliplatin or G6PD knockdown alone, which was evident by the significant reduced PDX tumor growth and tumor weight." (PMID 28692052, 2017). "Therefore, we subsequently used xenograft models in nude mice to investigate whether G6PD promotes RCC tumor growth in vivo." (PMID 29312589, 2017). "Likewise, a direct connection between tumor growth and G6PD was confirmed." (PMID 27872579, 2016). "Notably, survival of all these tumour-prone mouse lines was indistinguishable regardless of the presence of the G6PD-Tg allele." (PMID 26976705, 2016). "Furthermore, the tumor malignancy was observed to be in accord with G6PD protein expression." (PMID 23693134, 2013). "In humanized mouse models, PANX2 overexpression suppresses tumor growth-effects reversed by NRF2 knockdown, G6PD overexpression, or P2X7R blockade." (PMID 42210821, 2026). "In turn, E2F1 activates the glucose-6-phosphate dehydrogenease (G6PD) transcription, driving NADPH production and metabolic reprogramming to support tumor growth and metastasis." (PMID 41484982, 2026). "Subsequent experiments demonstrated a significant inhibition of tumor growth in vivo upon overexpression of BANCR, and G6PD played a pivotal role in mediating the tumor-suppressive effect of BANCR in ccRCC cells." (PMID 39894218, 2025). "Huh6 cells were subcutaneously transplanted into nude mice, which were monitored weekly for tumor size while receiving treatments with the YAP1 inhibitor Verteporfin, the NAT10 inhibitor Remodelin, and the G6PD inhibitor Fluasterone." (PMID 40303290, 2025). "Meanwhile, the upregulated G6PD expression by FOXO1 can promote PPP progression and further enhance the growth of tumor cells in vivo and in vitro." (PMID 41124013, 2025). "To validate these predictions, we performed RNA FISH testing in ccRCC cell lines and human ccRCC tumor tissues to examine the interaction between BANCR and G6PD." (PMID 39894218, 2025). "We found the increased expression of PFKP, TPX2, UBE2S, ST6GALNAC4, ADAM15, G6PD, and KPNA2, but decreased expression of GOT2 in tumor samples compared to normal samples." (PMID 40307857, 2025). "The results indicated that in tumor tissues with NAT10 overexpression and G6PD knockdown, the G6PD and Ki-67 expression were significantly lower." (PMID 40303290, 2025).